TNF (tumor necrosis factor)
Diseases named in the same sentence as TNF in open-access papers (continued):
Sharing a sentence is not in itself a finding about the gene and the disease.
tumor (continued). "By binding to its receptors TNF-αR-1 and TNF-αR-2, TNF-α promotes tumor proliferation and angiogenesis and induces the EMT of tumor cells." (PMID 38520006, 2024). "These inhibitors work by blocking the binding of PD-1 to its ligand PD-L1, restoring the anti-tumor activity of NK cells and T cells, and increasing their cytotoxicity and secretion of immune factors such as IFN-γ and TNF-α." (PMID 39906665, 2024). "Recent studies have shown that targeting TBK1 can reduce the sensitivity of tumor cells to effector cytokines (such as TNF-α and IFN-γ), promote tumor cell apoptosis, and reverse tumor resistance to immunotherapy." (PMID 39161768, 2024). "Activation of TLRs in NSCLC cells leads to upregulation of pro-inflammatory cytokines and chemokines (TNF-α or CCL2), contributing to the immunosuppressive nature of the tumor microenvironment." (PMID 38792335, 2024). "After THC treatment, a decrease was observed in the level of six cytokines in serum samples, including IL-6 and TNF-α, as well as chemokine (C-C motif) ligand 2 (CCL2), known for its unfavorable effects on tumor prognosis, and reviewed elsewhere." (PMID 38799159, 2024). "BECN1, ELAVL1, and ATG16L1 were highly expressed in tumor tissues, while NCOA4, FTH1, FTL, SNCA, TNF, ATG7, and ZFP36 showed low expression levels." (PMID 39593730, 2024). "Cytokines, including TNF-a, IFN-g, and IL-2, have been demonstrated to have anti-tumor effects in vitro." (PMID 39011219, 2024). "In addition, as inflammatory responses are indicated as a quite relevant factor in different stages of tumor development, the effect of both quinoxaline derivatives on mouse carrageenan peritonitis and levels of pro-inflammatory interleukin (IL)-1 β and tumor necrosis factor (TNF)-α were evaluated." (PMID 39109780, 2024). "The levels of TNF-α in tumor tissues and serum collected from patients with NSCLC substantially increase with the clinical stage of the tumor." (PMID 38918540, 2024). "Extensive evidence demonstrates that CD8+ CTLs and NK cells can identify and destroy tumor cells through the secretion of perforin, granzymes, and cytokines such as interferon-gamma (IFN-γ) and TNF-α 46, 49-52." (PMID 39664577, 2024). "AlloIgG combined with DC stimuli TNFα and CD40L induced tumor eradication via the reported and prospective signaling pathways." (PMID 38461238, 2024). "Increased TNF‐α expression, transcription, and release from cancer cells due to PRKCI‐induced nuclear translocation of YAP1 attracts MDSCs into the tumor beds." (PMID 38703051, 2024). "The proinflammatory cytokines IL-12 and TNFα were encapsulated in polylactic acid (PLA) microspheres and injected once i.t. in the weakly immunogenic MT-901 murine model of BC eleven days after tumor implantation." (PMID 38803496, 2024). "For instance, they release cytokines like IL-6 and TNF-α, or vascular endothelial growth factor (VEGF) and matrix metalloproteinases (MMP) that have been involved in cancer cell proliferation and tumor metastasis." (PMID 39256468, 2024). "In another study, combination therapy increased the production of functional cytokines IFNγ, TNFα, and granzyme B by CD8+ T cells in peripheral blood and tumor tissue." (PMID 38361936, 2024). "TNF has also been reported to upregulate IL‐17A production by CD4+ T cells, thereby recruiting myeloid cells into the TME and enhancing tumor growth." (PMID 38566518, 2024). "Th1 cells are generally considered as anti-tumor immune cells that inhibit tumor growth and activate tumor-specific immune mechanisms by producing IFN-γ, TNF-α, and IL-2." (PMID 38293522, 2024). "In general, tumor cells release interleukin-1 (IL-1), vascular endothelial growth factor (VEGF), tumor necrosis factor α(TNF-α), and other signaling molecules to induce inflammation in addition to coagulation." (PMID 38891849, 2024).
tumor (continued). "By measuring the expression of related target molecules and exploring the effect of a TNF-α inhibitor, we were able to experimentally verify the central role of the TNF pathway in the anti-tumor activity of the cordycepin and doxorubicin drug combination." (PMID 39000182, 2024). "Concurrently, IFN‐γ and TNF‐α levels, as well as NK cell and CD8+ T cell infiltration in tumor tissues were increased." (PMID 38234174, 2024). "S100A8/A9 can interact with PDAC cells and CAFs, leading to the expression of various pro-inflammatory cytokines (such as IL-6, IL-8, and TNF-α), while knockout of CD74 delay the growth of tumor." (PMID 38167055, 2024). "Increases M1 macrophages, enhances the expression of anti-tumor cytokines (IFN-γ, TNF-α, and IL-12), and reduces the level of pro-tumor cytokines (IL-10, IL-4, and TGF-β)." (PMID 38361933, 2024). "Inhibiting neutrophils or NETs enhances the expression of cytotoxic proteins like IFNγ and TNFα in CD8+ T cells, resulting in better tumor control." (PMID 39648199, 2024). "Another study highlighting neutrophil-killing potential demonstrated that combination therapy involving tumor necrosis factor, CD40 agonist, and a tumor-binding antibody induced rapid mobilization and tumor infiltration of neutrophils." (PMID 38474175, 2024). "Engineered cytokines, such as TNF-α-derived peptide and recombinant fusion IL-2 (ALKS 4320), have demonstrated less toxicity and effective inhibition of tumor growth in preclinical studies." (PMID 38256080, 2024). "Enterococcus faecalis, for example, has been shown to induce the expression of pro-inflammatory cytokines like TNF-alpha by activating p38 MAPK and NF-kB signaling pathways in macrophages, creating a tumor-promoting inflammatory environment." (PMID 39597645, 2024). "MPE-Tem and MPE-Tcm secreted more IFNγ, TNFα, and IL-2 compared to paired MPE-TemRA and MPE-Tnaive, which were used to kill tumor cells." (PMID 39372862, 2024). "Among the possible reasons for this is that TNF also signals via TNFR2, which has been shown to enhance anti-tumor immunity by inducing CD8+ T cell proliferation and function." (PMID 39178856, 2024). "In the case of cell-based therapy of GBM, (γδ) T cells seem to be a suitable subset of T cells due to their capability to infiltrate tumor tissue and anti-tumor activity (perforin–granzyme-mediated, expression of IFN-γ and TNFα)." (PMID 38786032, 2024). "CD137+ TRTs from all three samples showed considerably increased production of IFN-γ (p=0.0858, n=3) and TNF-α (p=0.0661, n=3) as well as upregulation of CD107a (p=0.0692, n=3) and CD137 (p=0.0836, n=3) upon co-culture with autologous tumor cell lines." (PMID 39717766, 2024). "EP_C1 cells exhibited immune-promoting properties with enhanced response to TNF and IFN-γ, as well as activated antigen processing and presentation, suggesting their pivotal role in tumor recognition and immune infiltration." (PMID 39105803, 2024). "Tumor-derived factors such as IL-6, TNF-α, IFN-γ, AZGP1, and PTHrP, and tumor-host interactions influence metabolic programs in adipose tissue, including browning, lipolysis, inflammation, and thermogenesis." (PMID 38245780, 2024). "In the presence of tumour cells, the MSLN CAR‐iNK cells show increased secretion of IFN‐γ and TNF‐α, as well as elevated cytotoxic degranulation level (CD107a expression) compared with iNK cells." (PMID 39136096, 2024). "MMPs (especially MMP9) stimulate tumor cell proliferation and the production of VEGF and subsequent angiogenesis, while IL-6, IL-1β, and TNF-α, among pro-inflammatory cytokines, support chronic inflammation preceding or associated with tumor." (PMID 38612841, 2024). "Consistent with the tumor sphere formation results, PRKCSH depletion also accelerated TRAIL- and TNF-α-mediated cell death in A549 cells." (PMID 38200153, 2024).
tumor (continued). "Gene set enrichment analysis (GSEA) revealed that the IL-6-STAT3 signaling pathway, inflammation, TNFα signaling, and angiogenesis-related pathways were all significantly induced by B16F10 tumour cell-derived EVPs." (PMID 38853850, 2024). "It has been reported that the tumor microenvironment of ACSL4−/− animal models displays decreased infiltration of CD8+, IFNγ+CD8+, TNFα+CD8+, and CD4+ T cells compared to the tumor microenvironment of ACSL4+/+ animal models." (PMID 38778030, 2024). "In direct comparison of tumor and healthy tissues, NFkB and VEGF were activated, whereas PI3K, TGF beta, and TNF alpha were inactivated." (PMID 38802361, 2024). "Vδ1 T cells induce apoptosis of tumor cells through cytotoxic mediators such as perforin and granzyme and by releasing IFN-γ and TNF-α." (PMID 38515134, 2024). "Exhausted T cells exhibit a decline in their cytotoxicity against tumor cells, accompanied by downregulation of IFN-γ and TNF-α expression." (PMID 39223632, 2024). "In our study, we found that SCGN is highly expressed mainly at the early stage of tumorigenesis, and SCGN can upregulate TNFα at an early stage, by NF-ĸB creating an inflammatory TME and thus recruiting M1-type macrophages to inhibit tumor progression." (PMID 39664565, 2024). "ELISA reveals that XLLXF combined with trastuzumab increases the levels of IL-15, IL-2, TNF-α, and IFN-γ in tumor-bearing mice." (PMID 38379418, 2024). "Compared to conventional CAR-T cells, CAR-ss-T cells produced higher levels of interferon-γ (IFN-γ), IL-2, tumor necrosis factor-α (TNF-α) and granzyme B (GZM) against MSLN-expressing HGC27 and MKN45 tumor cells." (PMID 38368374, 2024). "M1 macrophages secrete pro-inflammatory cytokines, such as IL-12, TNF-α, CXCL-10, and IFN-γ, and produce high levels of iNOS to eliminate tumor cells." (PMID 38550587, 2024). "The requirement of IFN-γ and TNF-⍺/IL-1β for the upregulation of NOS2 and COX2 in human tumor cells implies that the microenvironment inducing NOS2-rich regions requires cells present that are releasing IFN-γ and other proinflammatory cytokines." (PMID 38892290, 2024). "Promising clinical results have shown that VOV treatment increases tumor necrosis factor (TNF-α) levels and IFN-γ at tumor sites." (PMID 39340040, 2024). "This leads to the enhanced secretion of IFN-γ, TNF-α, Granzyme B, and Perforin, which in turn boosts the cytotoxic function of CD8+ T cells, promoting more effective tumor destruction." (PMID 38184630, 2024). "Radiotherapy has been shown to be associated with upregulation of genes involved in proliferation and migration of tumor cells (CXCL12, VEGF-A, TGF-β1, and TNFα)." (PMID 38256907, 2024). "The increased expression of TNF-α seems to be correlated with high levels of β-catenin and SNAIL at the tumor-stromal boundary of dissociating cancer cells." (PMID 39201656, 2024). "Taken together, increased M1 macrophage markers TNF-α and iNOS and apoptosis induction in HepG2 cells and macrophages from IFN-β-exposed liver tumor organoids suggest the selective tumor therapeutic potential of IFN-β." (PMID 38279326, 2024). "IL-12 modulates the TME by inducing other cytokines including interferon (IFN)-γ and tumor necrosis factor (TNF)-ɑ, improving Th1-type response and suppressing tumor-induced Treg cell proliferation." (PMID 39711794, 2024). "The summary of signaling pathway shows that ADAM17 activation is associated with many signaling pathways, such as inflammation response (e.g. IL-6, IL-1β, TNF, and TGF-β1), migration of tumor cells, tissue wound, and extracellular matrix organization." (PMID 38341954, 2024). "This process leads to the activation of pro-inflammatory pathways, including the production of cytokines such as interleukin-6 (IL-6) and tumor necrosis factor-alpha (TNF-alpha), which can promote tumor growth and metastasis." (PMID 39272881, 2024).
tumor (continued). "Assessment of T cell-mediated antitumor responses in tumor tissues showed that knockdown of ELF3 increased CD8+ T cell infiltration and elevated the levels of TNF-α and IFN-γ in tumor tissue homogenates." (PMID 39219440, 2024). "Phosphorylation of STAT1 can facilitate the macrophage differentiation into M1 phenotype, which has anti-tumor effects and can secrete substantial inflammatory cytokines, including IFN-γ, TNF-α and IL-1β." (PMID 38244580, 2024). "Later evidence supports the notion that Mb-TNF-α is indeed involved in MDSCs infiltration to the tumor site, as TNFR2 stimulation by Mb-TNF-α up-regulates several chemokines and chemokine receptors." (PMID 39609700, 2024). "We isolated tumor cells from mice treated with SMC and α-PD-1 that reached endpoint and evaluated for their responsiveness to LCL161 and TNF-α treatment ex vivo." (PMID 39147758, 2024). "In the context of serial co-cultures with OVCAR-3 or MCF7 tumour cells, FOXO1 overexpression led to a significant increase in the recovery of CD8+ and CD4+ CAR T cells and similar levels of IFNγ and TNF production compared with control CAR T cells." (PMID 38600376, 2024). "They showed that high levels of TNFα in the tumor microenvironment promote EMT by upregulating the transcriptional regulator Snail, promoting tumor invasion, and indirectly reducing DFS." (PMID 38927889, 2024). "M2-like TAMs are primarily activated by IL-10 and TGF-β, expressing CD163, CD204 and CD206, secrete IL-10, TNF, CCL17, among others, which exerting pro-tumor effects." (PMID 38270700, 2024). "BMAs secrete adipocytokines such as leptin, adiponectin, IL-1β, IL-6, VCAM-1, TNF-α, and VEGF to promote tumor cell metastasis." (PMID 38770000, 2024). "Consistent with the regulon profile, tumor-reactive T cells exhibited higher expression of pro-inflammatory effector molecules such as IFNG, TNF, and PRF1 and lower expression of genes like LBT, CD27, and CD28." (PMID 39243082, 2024). "The KEGG analysis of core targets indicated that BZYQ affects multiple signaling pathways related to tumor and inflammation in the treatment of CRF, including TNF, IL-17, Toll-like receptor (TLR), NF-κB, and C-type lectin receptor (CLR) signaling pathways." (PMID 39564104, 2024). "Tumors recruit the hemocytes, which bear the TNF-α (Egr) signal, to the TME, resulting in activation of JNK signaling in tumor cells." (PMID 39642218, 2024). "TNF-α and TNF-β have similar functions, both of which can stimulate and regulate inflammatory response, anti-tumor, anti-virus, etc., and can also induce the generation of new blood vessels." (PMID 38848433, 2024). "Ligands for FFAR2 (G protein-coupled receptor 43, GPR43) inhibit the TNF-α signaling pathway, thus FFAR2 − TNF being upregulated signifies the suppressive effect of VCAN+ TAMs on anti-tumor immunity." (PMID 39232806, 2024). "It was also found that the combined function of IFN-γ, TNF-α, and IL-1β will stimulate CCL22 secretion by tumor cells." (PMID 39003350, 2024). "Studies have shown that reducing TNF-α and IL-6 levels and increasing IFN-γ can help inhibit inflammation and tumor cell proliferation." (PMID 39508039, 2024). "DUSP1 expression was decreased in tumor tissue whereas TNF, NOX4, and LONP1 expressions were increased in tumor tissue, compared with those in normal tissue." (PMID 38758860, 2024). "TNF-, FasL-, and TRAIL-induced tumoricidal function of DCs is activated as these cells arrive in the tumor beds." (PMID 38903193, 2024). "It upregulates cytokines like IL-6 and TNF-α and downregulates miRNA18a via the TLR-4/MYD88 pathway, further supporting tumor growth and immune evasion." (PMID 39273009, 2024).
tumor (continued). "Various inflammatory cytokines such as tumor necrosis factor α (TNF-α), interleukin-6 (IL-6), interleukin-1 α (IL-1α), and interferon-γ (IFN-γ), produced by either tumor or host cells, can serve as triggers for these pathways." (PMID 38921029, 2024). "Activated NK cells are cytotoxic to tumor cells and produce immunomodulatory cytokines, such as interferon (IFN)-γ and a tumor necrosis factor (TNF)-α." (PMID 38892084, 2024). "Inhibition of Cytokine Production: Elevated cholesterol levels interfere with the production of key cytokines such as Interferon-γ (IFN-γ) and Tumor Necrosis Factor-α (TNF-α), which are critical for NK cell-mediated tumor cell killing." (PMID 39351089, 2024). "Following the co-culture, we measured the levels of Tumor Necrosis Factor-α (TNFα), Interferon-γ (IFNγ) and Interleukin-2 (IL2), important for T-cell anti-tumor activity and proliferation." (PMID 39512355, 2024). "Tumor-derived PGE2 and TGF-β were shown to act in synergy to inhibit the production of IFN-α and TNF-α induced in TLR7- and TLR9-triggered pDCs, by decreasing TLR membrane expression or by blocking TLR downstream signaling." (PMID 38504978, 2024). "In inflammatory or tumor environments, inflammatory cytokines such as IFN-γ, IL-6, and TNF-α can increase the activity of indoleamine 2,3-dioxygenase (IDO)." (PMID 39156806, 2024). "γδ T cells stimulate immune responses indirectly by secreting cytokines like interferon-γ (IFN-γ), tumor necrosis factor-α (TNF-α), interleukin (IL)-2, IL-10, IL-12, and IL-15, impacting both tumor cells and the microenvironment." (PMID 39748921, 2024). "The degree and success rate of anti-tumor immune response are determined by the synergistic effect of multiple cytokines in TIME, and TNF-α, TGF-β and IFN-γ are the cytokines that are often concerned." (PMID 38361933, 2024). "At the same time, we found that the number of perforin, granzyme B, IFN-γ, and TNF-α released from between CT26 (Ctrl) and CT26 KO tumor tissue was significant." (PMID 38740747, 2024). "In co-culture with tumor cells and monocytes, stCAR T cells exhibited anti-tumoral activity and potent release of CRS-related cytokines (IL-6, IFN-γ, TNF-α, GM-CSF, IL-2, IL-10)." (PMID 38514793, 2024). "In describing the role of the immune system in HCC, Giuseppe made it clear that IL-1, TNF-α, and IL-6 are involved in invasion and metastasis, whereas TGF-β and IL-20 reduce the anti-tumor immune response." (PMID 38699038, 2024). "In addition, we verified other NF-κB downstream genes (VEGFA, TNFα, and uPA) which involved in the regulation of tumor microenvironment and found that GATA4 can also down-regulate their mRNA levels, suggesting that GATA4 may be a potential factor in the regulation of tumor microenvironment." (PMID 38653973, 2024). "In a single-cell study of T-cell phenotypes in supercentenarians linking high fractions of CD4+ cytotoxic T-cells to repeated viral exposure and favourable anti-tumor immunity, extracted CD4+ cytotoxic T-cells secreted TNF-α and IFN-γ upon ex vivo stimulation." (PMID 38049509, 2024). "Tumor cells can also induce T-cell exhaustion by inhibiting the expression of miR-28 and miR-150, which are involved in the production of IFN-γ, IL-2, and TNF-α, as well as the repression of PD-1 in T cells." (PMID 38473997, 2024). "This therapy strategy employs TNF to promote the recruitment of neutrophils to tumors, coupled with the use of CD40 agonists to activate the tumor-killing functions of neutrophils." (PMID 38523155, 2024). "Compared to the control group, the PRKCSH-depleted group of A549 cells showed dose-dependent reductions in tumor sphere formation in response to both TRAIL and TNF-α." (PMID 38200153, 2024). "Although cytokine production from CD4-positive T cells in the tumor was deemed insignificant 24 days post-tumor inoculation, CD8-positive T cells exhibited a notably increased IFN-γ and TNF-α production." (PMID 38523774, 2024).